ANXA2 (annexin A2)
Diseases named in the same sentence as ANXA2 in open-access papers (continued):
Sharing a sentence is not in itself a finding about the gene and the disease.
cancer (continued). "Annexin A2 is a multifunctional protein that has been shown to be overexpressed in a large number of cancers (e.g., breast, liver, gastric, pancreatic, lung, gliomas, colorectal, and ovarian) and to be positively associated with metastasis and resistance to chemotherapy." (PMID 26682014, 2016). "Tyrosine phosphorylation of Anxa2 is critical for cancer cell migration and invasion." (PMID 27754360, 2016). "We found that Src inhibitor could downregulate Annexin A2 phosphorylation, indicating that Src could phosphorylate Annexin A2 in cancer cells." (PMID 26716413, 2016). "ANXA2 is a calcium-binding cytoskeletal protein aberrantly expressed in a wide spectrum of cancers and in EOC may promote cell proliferation." (PMID 27259239, 2016). "Indeed, increased expression of ANXA2 and its positive correlation with cell migration and invasion have been described in several types of cancers including colorectal, pancreatic, breast and renal cancer, gastric carcinoma and vascular tumors." (PMID 27429043, 2016). "Recent studies have shown that curcumin potentially inhibits Annexin A2 in cancer tissues." (PMID 27845899, 2016). "ANXA2 is aberrantly expressed in many types of cancer, including HCC." (PMID 27385217, 2016). "Decreased annexin A2 expression in cancer cells could play a role in the progression and metastasis of CRC and may be useful for predicting metastasis." (PMID 27468721, 2016). "ANXA2 is closely related to the occurrence and development of tumors, and also plays an important role in angiogenesis, proliferation, apoptosis, adhesion, invasion, and migration in malignant tumors." (PMID 26362938, 2015). "Annexin A2 (ANXA2) expression is highly upregulated in many types of cancer." (PMID 25611381, 2015). "Anxa2 overexpression has been reported in many malignant tumors." (PMID 26307676, 2015). "Our findings place MIEN1 and anxA2 as attractive therapeutic targets for blocking invasive cancers." (PMID 26272794, 2015). "While ANXA2 has been shown to play roles in the nucleus, its function as an interface between cytoplasmic signaling events and the plasminogen/plasmin system are well known in vascular biology and cancer studies." (PMID 24465474, 2014). "The upregulation of ANXA2 in cancer may have several clinical applications, including as a diagnostic marker for early detection, a predictive factor for prognosis, or a marker for drug resistance." (PMID 24591759, 2014). "Increased expression of ANXA2 is frequently observed in a broad spectrum of cancer cells." (PMID 24591759, 2014). "ANXA2 expression levels vary among different types of cancers." (PMID 24591759, 2014). "We observed enhanced activation of the pro-apoptotic kinases p38, JNK and Akt in the annexin A2-depleted cancer cells treated with H2O2 compared to control cells; these protein kinases serve as reporters for the activity of the Ask-1 and PI3K signalling pathways, respectively." (PMID 23434659, 2013). "The redox function of annexin A2 may be relevant in designing novel can cancer therapeutics that are aimed at increasing the effectiveness of radiation and chemotherapeutics which largely function by increasing ROS levels." (PMID 23519104, 2013). "This not only reflects the lack of complete understanding of annexin A2 regulation in tumors but also the fact that annexin A2 deregulation is probably affecting gene expression or is simply a bystander effect as a consequence of change in expression of major cancer-regulating genes." (PMID 23519104, 2013). "Therefore, annexin A2 contributes to cancer progression by enhancing cancer cell motility, invasion and adhesion." (PMID 23945256, 2013). "Depletion of annexin A2 in Fe-NTA-induced RCC cell lines resulted in apoptosis, suggesting that the ROS buffering function of annexin A2 might play an important role in this cancer cell model." (PMID 23434659, 2013).
cancer (continued). "Annexin A2 also plays an important role in the plasminogen activation system and acts as a tissue plasminogen activator (t-PA) receptor on the cell surface of endothelial and cancer cells, which mediates the conversion of plasminogen into plasmin." (PMID 23945256, 2013). "As a final note, alterations in AnxA2 expression or activity have been demonstrated in many different cancers, particularly those of the prostate, the breast, the liver, the lung (there are too many references to cite meaningfully here), and in the formation of infective HIV particles." (PMID 22505935, 2012). "Cell surface expression of annexin A2 is required for invasion and metastasis in cancer." (PMID 22359590, 2012). "In addition, we evaluated the effect of AnxA2 knockdown on cancer cell growth and colony formation by a focus formation assay and found significantly fewer foci as compared to vector control (p<0.005)." (PMID 22957061, 2012). "The observed increased sensitivity of ANXA2 depleted cells to death induced by chemotherapeutics that up-regulate ROS led us to postulate that blocking the expression of ANXA2 in cancer cells might constitute a potential therapeutic strategy." (PMID 22185818, 2011). "Annexin A2 (ANXA2) is another important cancer gene under the control of p16 and AUF1." (PMID 21799732, 2011). "Furthermore, the growth of tumors resulting from the subcutaneous injection of ANXA2-depleted human cancer cell lines, HT1080 and A549, in mice showed severe growth impairment compared to control cells." (PMID 22185818, 2011). "Furthermore, the volume of tumors grown from ANXA2 depleted A549 cancer cells was 70% smaller compared to A549 control tumors." (PMID 22185818, 2011). "It is of interest that ANXA2, a membrane trafficking protein, was over-expressed in our resistant cells, since its up-regulation has already been reported in a doxorubicin-resistant cancer cell line." (PMID 17477866, 2007). "Besides, we showed that membrane repair of these cancer cells is strictly dependent on the presence of ANXA2, whether the type of membrane damage either by laser ablation or shear stress." (PMID 38092984, 2023). "Therefore, this intriguing observation encourages investigating whether the role of ANXA2, and ANXA5 in the nucleus of cancer cells, either contribute to carcinogenesis or is associated with an anticancer mechanism." (PMID 37117324, 2023). "The enhancer linked to ANXA2 is significantly enriched in the cancer-epithelial cells but not in the non-malignant cell types (log2FC = 2.3 and FDR < 0.001), resulting in significantly higher expression of ANXA2 as measured by the scRNA-seq (Wilcoxon rank sum tests, p-value < 2.22 × 10−16)." (PMID 37685859, 2023). "In addition, this study showed both cancer cells and cancer associated fibroblasts express phosphorylated Annexin A2, whereas normal fibroblasts do not." (PMID 37941562, 2023). "Interestingly, exosomal-annexin A2 also contributes to elicit cancer promotable macrophages." (PMID 37091157, 2023). "Furthermore, these findings go some way to explain the molecular mechanisms and associated biological processes that Annexin A2 phosphorylation mediates in the TME, and how these are plausibly connected to aggressive disease and cancer metastasis, as seen in our previous work, and that of others." (PMID 37941562, 2023). "Inhibiting ANXA2 may promote efficacy of bleomycin for cancer treatment." (PMID 33995636, 2021). "Interestingly, AHNAK has been implicated in the regulation of cell membrane cytoarchitecture, as well as pseudopod protrusion via interaction with Annexin A2, septin-9, and Ca2+-dependent S100 proteins, which have both been shown to contribute to cancer metastasis." (PMID 33564071, 2021).
cancer (continued). "Two Annexin A2 monomers bridged by an S100A10 homodimer are known to form a multifunctional membrane-associated heterotetramer, which has been implicated in membrane trafficking events and membrane-cytoskeletal connection relating to cell motility and drug-resistance in human cancers." (PMID 32154176, 2020). "Additionally, phosphorylated Anxa2 confers resistance in several cancer cells." (PMID 31113450, 2019). "Although ANXA2-targeted therapy suppresses cancers, it may produce side effects in patients." (PMID 29598816, 2018). "Moreover, intracellular Annexin A2 promotes autophagy and NF-кB activation, which suggested that multi-drug resistance might arise from the over-expression of Annexin A2 in cancer cells." (PMID 28963461, 2017). "Here, we demonstrated for the first time that (20S)G-Rh2 directly binds to Annexin A2, which interfered the interaction between Annexin A2 and NF-кB p50 subunit, and thus, down-regulated NF-кB activation and anti-apoptosis gene expression, finally promoted apoptosis in cancer cells." (PMID 28963461, 2017). "Overexpression of AnxA2 (as is seen in some cancers) or nonstoichiometric changes in the relative concentrations of AnxA2 and S100A10 may have more severe phenotypes than loss of both." (PMID 22505935, 2012). "It appears that the major defects in the mouse are not in normal development; but rather in subsequent plastic changes: the mouse seems to be incapable of sustaining neovascularisation, for example, which may make AnxA2 a promising target for drug intervention in cancer treatment." (PMID 22505935, 2012). "Our results indicate that ANXA2 activates the Akt/mTOR signaling pathway and EMT in ESCC, thereby enhancing cancer invasion and metastasis through the regulation of β-catenin, Snail, and Claudin-1 proteins." (PMID 38658569, 2024). "Through its interaction with EGFR on the cell surface, ANXA2 regulates the activation of EGFR and the downstream PI3K-AKT signaling pathway, which is important for malignant phenotypes, such as cancer cell proliferation and migration." (PMID 39333871, 2024). "We previously revealed that lysyl oxidase-like 4 (LOXL4) promotes the invasiveness of TNBC cells via cell surface annexin A2 as a novel binding substrate of LOXL4, which promotes the abundant localization of integrin-β1 at the cancer plasma membrane." (PMID 38863623, 2024). "LncRNA LUCAT1 inhibits phosphorylation of annexin A2, further inhibiting the degradation of ANXA2-S100A10 heterotetramer (AIIT) and promoting cancer development." (PMID 39539540, 2024). "Expression of the annexin family had beenstudied in a wide range of cancers, including ANXA1, ANXA2 and ANXA13 Annexin familymembers were involved in signal transduction, cellular differentiation,proliferation and thus in tumorigenesis (Lizarbe etal., 2013)." (PMID 38626574, 2024). "This approach has also been applied to design anti-cancer peptides from proteins like MIEN1 and Annexin A2, which are specific to cancer cells." (PMID 39590524, 2024). "The molecular mechanism by which Anxa2 participates in RCC involves regulating the cytoskeletal remodeling of actin and promoting cancer cell motility." (PMID 37955107, 2023). "The ANXA2 expression was significantly associated with the infiltration of six immune cells (B cells, dendritic cells, macrophages, neutrophils, NK cells and T cells) in BLCA, PCPG, PRAD, TGCT and THCA, indicating that ANXA2 might influence the immune responses in these six types of cancer." (PMID 36713082, 2023). "We further investigated the correlation between ANXA2 expression and TMB, MSI and MMR in 33 types of cancer." (PMID 36713082, 2023). "Annexin A2 (ANXA2), a member of the annexin family of proteins, is expressed on the surface of various types of cancer cells." (PMID 36916296, 2023).
cancer (continued). "Stromal protein expression changed primarily during the transition from SBT to LGSC (629 differentially expressed proteins), including the upregulation of ANXA2 and its regulator S100A10, which play a central role in cancer cell proliferation." (PMID 38014221, 2023). "Due to the vital role played by lysosomes in cancer, a LRRS signature was constructed, including 8 genes, namely, CLN3, GBA, CTSA, BSG, APLN, SORT1, ANXA2, and LAPTM4B." (PMID 38114725, 2023). "Our work demonstrates that Annexin A2 has a distinct role in mediating the dynamic reciprocity between the ECM and cancer cells." (PMID 37941562, 2023). "Co-treatment with annexin A2 inhibitors such as matrine, LGRFYAASG peptide, or siRNA to annexin A2 has been shown to improve outcomes from various cancer scenarios." (PMID 35163891, 2022). "Annexin A2 (ANXA2) is a group of calcium-dependent phospholipid-binding proteins that are expressed in several cell types, including mononuclear cells, cancer cells, and bone cells." (PMID 36293376, 2022). "Annexin A2, which can bind to the Vδ3 TCR, is expressed in multiple cancer cell types, including endometrial, breast, and glioblastoma cells." (PMID 33707742, 2021). "Annexin A2 (ANXA2) belongs to annexin superfamily of Ca2+-dependent phospholipid–binding proteins and is involved in invasion, angiogenesis and migration in cancer cells." (PMID 34048174, 2021). "We then utilized the available data within the Cancer Cell Line Encyclopedia (CCLE) to further probe the relationship between ER status and AnxA2 expression." (PMID 32629869, 2020). "Annexin A2 (ANX A2), which is a membrane-binding protein involved in cell adhesion, is known to promote cancer invasion." (PMID 32509366, 2020). "In cancer cells, TGF‐β stimulation increased ANXA2 expression and phosphorylation, and phosphorylated ANXA2 activated the STAT3 pathway, resulting in EMT and invasion." (PMID 33005848, 2020). "Annexin A2 (ANX A2), a membrane-binding protein, promotes cancer invasion and is involved in cell adhesion and polarity." (PMID 31485361, 2019). "The results showed interaction between HE4/ANXA2 and MMP2 was common in various malignant tumor cells including CaoV3, ES-2, OVCAR-3, Ishikawa, A549, HGC-27, SW480, HepG2, Hela, HT29 and HEK293 cell lines." (PMID 31210752, 2019). "ANXA2 and KRAS were also direct downstream targets of miR-206 that modulated cancer cell growth, metastasis, and lymphangiogenesis in PDAC." (PMID 30700038, 2019). "The results of the double-label immunofluorescence assay showed that the co-localization of HE4/ANXA2 was on the cytoplasm and membrane of HEK293 and various malignant tumor cells including SW480, ES-2, A549, HT29 and HGC-27." (PMID 31210752, 2019). "In contrast to mesothelin, for which limited data supports its biological role in PDAC development, ANXA2 is biologically essential for PDAC metastasis and the development of many other cancer types." (PMID 31113479, 2019). "By binding to extracellular partners like annexin A2 and transglutaminase-2, S100A4 can also hinder cell-ECM adhesion of cancer cells." (PMID 31652274, 2019). "IGFs that are secreted from stromal cells can act on cancer cells via direct IGF-1R signaling, and together with hepatocyte growth factor/HGF, can phosphorylate Annexin A2/AnxA2, a protein that has a well-established role in invasion/metastasis." (PMID 29475434, 2018). "Increased expression of annexin A2 and S100A10 in cancer cells leads to increased levels of plasmin—which promotes the degradation of the extracellular matrix—increased angiogenesis, and the invasion of the surrounding organs." (PMID 30572596, 2018). "The expression of ANXA2 and CDH1 was evaluated in cancer (at different stages) and healthy datasets." (PMID 30050103, 2018). "Thus, Annexin A2 might be a promising molecular target for cancer therapy." (PMID 28963461, 2017).
cancer (continued). "ANXA2 expression was lower in cancer tissue (p = 0.002), whereas ANXA4 staining increased significantly in cancer tissues (p < 0.001)." (PMID 27402115, 2016). "Dysregulation of Annexin A2 and STAT3 has been reported to take effects on cancer progression, metastasis, and prognosis, particularly in CRC." (PMID 27274723, 2016). "Taken together, silencing of ANXA2 inactivate Akt pathway and repress NPC cancer stem cells through inhibiting expression of Sox2, Nanog and Oct4." (PMID 26196246, 2015). "ANXA2 also interacted with P-gp and HAb18G/CD147 to promote malignant biological behavior of malignant tumors, such as drug resistance, proliferation, and adhesion." (PMID 26362938, 2015). "These interesting findings indicate that the interaction between P-gp and Anxa2 possibly plays an important role in driving the invasion and migration of MDR cancer cells." (PMID 23691462, 2012). "We extended our studies to TNBC phenotype and validated the importance of AnxA2 in the EGFR receptor protein complex and consequent signaling cascade leading to cancer cell migration, proliferation and apoptosis." (PMID 22957061, 2012). "ETV4, as a canonical transcription factor, could mediate the development and progression in multiple cancers through transcriptionally regulating its targeted genes, such as Cyclin D1, CXCR4, ANXA2 and KDM5D39-42." (PMID 41281746, 2025). "Other intriguing research showed that BC patients had greater levels of serum exosomal-annexin A2 (exo-AnxA2) than females without cancer, particularly for triple-negative BC (TNBC) as opposed to luminal and HER2-positive BC." (PMID 40305328, 2025). "Additionally, exosomal LINC00659 can promote cancer cell proliferation, invasion, migration, and EMT progression by interacting directly with miR-342-3p and increasing Annexin A2 (ANXA2) expression in CRC cells." (PMID 39684264, 2024). "Collectively, our findings suggest that the NASP/ANXA2/STAT3 axis is a potential therapeutic target for improving the prognosis of patients with GBM, which has important implications for the development of more effective and precise cancer treatments." (PMID 38605477, 2024). "In addition, as demonstrated in our study and previous studies, ANXA2 is also abundantly expressed in other types of cancers, making Cy7‐YW7 a potentially valuable probe to detect other ANXA2‐positive cancers." (PMID 36453020, 2023). "Besides annexin A2, we also fortuitously exploited to identify the additional LOXL4 substrate protein on the cancer cell surface, which is conceivable to act to dampen NK cell activation (our unpubl." (PMID 37091157, 2023). "Similarly, the expression of ANXA2 negatively correlated with OS, PFI and DSS in seven types of cancer, including BLCA, HNSC, LGG, LUAD, MESO, PAAD and UVM." (PMID 36713082, 2023). "Contrary to these findings, cell-surface annexin A2 seems to have a negative aspect on cancer progression." (PMID 37091157, 2023). "The gene expression of ANXA2 was related to the clinical T stage of ACC, BRCA, HNSC, KIRC and THCA, the clinical M stage of BLCA, CESC, CHOL, LUAD and THCA and the clinical N stage of ACC, CESC, KIRP and LUSC in 33 types of cancer." (PMID 36713082, 2023). "Some molecules associated with γδ T cell activation such as the Butyrophilin (BTN)-family, UL16 Binding Protein (ULBP)-family, MHC Class I Polypeptide-Related Sequence A (MICA) and B (MICB), Annexin A2 (ANXA2), and Apolipoprotein A1 (APOA1 were lower in cancer organoids." (PMID 38090581, 2023). "Another protein, Annexin A2 (Anxa2), which has been found to co-localize and co-immunoprecipitate with P-gp in MCF-7/ADR cells, interacts with P-gp resulting in enhanced malignant phenotype of cancer cells." (PMID 36325145, 2022). "We found 16 proteins including HP, PKM, ANXA2, THBS1 that are differentially abundant in GBC tissue (literature search and unpublished data from our lab), in plasma and plasma-derived EVs from GBC or other cancer patients." (PMID 36505879, 2022).